CHMP7 (charged multivesicular body protein 7)
Description:
ESCRT-III-like protein required to recruit the ESCRT-III complex to the nuclear envelope (NE) during late anaphase. Together with SPAST, the ESCRT-III complex promotes NE sealing and mitotic spindle disassembly during late anaphase. Recruited to the reforming NE during anaphase by LEMD2. Plays a role in the endosomal sorting pathway.
Synonyms: MGC29816
Tractability: Antibody: its Gene Ontology location is reachable by antibodies, with high confidence. PROTAC: ubiquitination databases record sites on it; its protein half-life has been measured.
Gene: Protein-coding gene on chromosome 8 (23,243,635 to 23,266,156, forward strand). Ensembl gene ENSG00000147457.
Subcellular location: Cytoplasm; Nucleus envelope
Subcellular location (Human Protein Atlas): Nucleoplasm; Cytosol
Pathways (Reactome):
Disease: Budding and maturation of HIV virion; HCMV Late Events; Translation of Replicase and Assembly of the Replication Transcription Complex
Autophagy: Late endosomal microautophagy; Macroautophagy
Cell Cycle: Sealing of the nuclear envelope (NE) by ESCRT-III
Programmed Cell Death: Pyroptosis
Vesicle-mediated transport: Endosomal Sorting Complex Required For Transport (ESCRT)
Gene Ontology:
Molecular function: protein binding
Biological process: autophagosome maturation; autophagy; exit from mitosis; late endosome to lysosome transport; late endosome to vacuole transport; midbody abscission; mitotic metaphase chromosome alignment; multivesicular body sorting pathway; nuclear membrane reassembly; nucleus organization; plasma membrane repair; protein localization to chromatin; regulation of mitotic spindle assembly; ubiquitin-dependent protein catabolic process via the multivesicular body sorting pathway; viral budding from plasma membrane; viral budding via host ESCRT complex; ESCRT III complex disassembly; late endosome to vacuole transport via multivesicular body sorting pathway; membrane fission; multivesicular body assembly; multivesicular body-lysosome fusion; vesicle fusion with vacuole; vacuolar transport
Cellular component: amphisome membrane; autophagosome membrane; chromatin; cytoplasm; cytosol; ESCRT III complex; kinetochore; kinetochore microtubule; lysosomal membrane; midbody; multivesicular body membrane; nuclear envelope; nuclear pore; nucleoplasm; plasma membrane; cytoplasmic side of plasma membrane; nucleus
Genetic constraint (gnomAD): Loss-of-function variants: 13 observed, 41.64 expected, observed/expected ratio (o/e) 0.31, 90% interval 0.2 to 0.5. The upper end of that interval is the gene's LOEUF score, 0.5, which puts it in group 2 of 6, group 1 being the genes least tolerant of losing a copy. Missense variants: 487 observed, 501.4 expected, observed/expected ratio (o/e) 0.97, 90% interval 0.9 to 1.05. Synonymous variants: 247 observed, 204.92 expected, observed/expected ratio (o/e) 1.21, 90% interval 1.09 to 1.34.
Homologues: Orthologues: macaque CHMP7 (99% identical), chimpanzee CHMP7 (99% identical), dog CHMP7 (97% identical), pig CHMP7 (96% identical), rat Chmp7 (96% identical), guinea pig CHMP7 (95% identical), rabbit CHMP7 (95% identical), mouse Chmp7 (95% identical), zebrafish chmp7 (51% identical), tropical clawed frog chmp7 (47% identical). Paralogues in human: CHMP4C (13% identical), CHMP4B (12% identical), CHMP4A (12% identical), CHMP5 (11% identical), CHMP4BP1 (9% identical).